CD68 (CD68 molecule)
Diseases named in the same sentence as CD68 in open-access papers (continued):
Sharing a sentence is not in itself a finding about the gene and the disease.
Sandhoff disease (1 paper, 2007). A lysosomal disorder from the GM2 gangliosidosis family, caused by biallelic pathogenic variants in the HEXB gene, characterized by GM2 ganglioside accumulation in the nervous system and progressive central nervous system degeneration. "In the Sandhoff disease mouse model, microglial activation was shown to precede neurodegeneration and was associated with upregulation of macrophage markers CD68/macrosialin, galectin 3, cathepsins S and C, Mpeg1, and glycoprotein49a, which we also observed." (PMID 18021406, 2007).
SARS-CoV infection (1 paper, 2014). "The frequency of distinct lung leukocyte populations, including macrophages (CD68 + HLADR+), dendritic cells (DCs; CD68-HLADR + CD11c+), CD8 T lymphocytes (CD3 + CD8+), and B cells (CD3-CD20+) differed in the two age groups during SARS-CoV infection." (PMID 24642138, 2014).
Sciatica (1 paper, 2020). Pain in the lower back and hip radiating in the distribution of the sciatic nerve. "Disc tissue of 119 sciatica patients was embedded in paraffin and stained with hematoxylin and CD68." (PMID 31802274, 2020).
sialidosis (1 paper, 2023). "Since tissue infiltration with immune cells was previously reported for patients with sialidosis, kidney tissues were examined by immunohistochemistry for the presence of CD68-positive macrophages." (PMID 37698928, 2023).
skeletal muscle tumors (1 paper, 2025). "AE1/AE3 serves as an epithelial tumor marker, Vimentin identifies fibroblasts, CD68 highlights monocytes, histiocytes, osteoclasts, mast cells, and giant cells, and Desmin is specific for skeletal muscle tumors." (PMID 41333207, 2025).
skin changes (1 paper, 2024). "The gene sets encompass numerous genes previously implicated in the pathogenesis of SSc, such as Acta2, Col1a1, Col3a1, Smad3, Ctgf, Msr1, Cd4, Cd8a and Cd68, supporting the potential of anti-PRMT5 in induction of SSc-like skin changes." (PMID 38684324, 2024).
skin reaction (1 paper, 2020). "In parallel, a significant increase of CD15+ neutrophils, c‐kit/CD117+ mast cells, CD68+ macrophages and monocytes in the dermis of paradoxical skin reactions was observed (~3.8‐, 3.5‐, and 1.8‐fold increase, respectively)." (PMID 31577850, 2020).
skin tumors (1 paper, 2022). "In summary, this study shows that in subjects with persistent KS after ~180–280 days of ART, HIV diversity is maintained, RNA transcripts are expressed and spliced, and HIV Nef protein is localized to CD68+ macrophages in KS skin tumors." (PMID 36560778, 2022). "Our results show that in subjects with persistent KS after ~180–280 days of ART, HIV-DNA diversity was maintained, spliced RNA transcripts continued to be produced, and HIV Nef protein appears localized to CD68+ macrophages in KS skin tumors." (PMID 36560778, 2022).
spinal cord injury (1 paper, 2020). Penetrating and non-penetrating injuries to the spinal cord resulting from traumatic external forces (e.g., WOUNDS, GUNSHOT; WHIPLASH INJURIES; etc.). "Spinal cord injury (SCI) initiates a severe, destructive inflammation with pro-inflammatory, CD68+/CD163−, phagocytic macrophages infiltrating the area of necrosis and hemorrhage by day 3 and persisting for the next 16 weeks." (PMID 32977430, 2020).
spinal meningioma (1 paper, 2022). Spinal meningioma isa rare type of spinal cord cancer. "CD68+ staining was observed in 88 (71.5%) of the spinal meningioma group, and in 288 (68.9%) of the cranial meningiomas." (PMID 35205781, 2022). "Moreover, reduced density of CD68+ macrophage infiltrates was observed in the cohort of spinal meningiomas." (PMID 35205781, 2022). "Univariable analysis revealed that spinal meningioma patients are significantly older, had a worse baseline Karnofsky Performance Status (KPS), higher acute-phase protein levels, lower incidence of WHO grade 2, lower mitotic counts, lower MIB-1 index, and less CD68+ macrophage infiltrates." (PMID 35205781, 2022).
spinal stenosis (1 paper, 2023). Narrowing of the spinal canal. "CD68-stained macrophages were also not observed in the group implanted with a catheter for spinal stenosis." (PMID 37239061, 2023).
spinal tuberculosis (1 paper, 2024). "CD4+ and CD8+ T cells were detected in HIV-negative spinal tuberculosis tissue sections, along with a population of CD68-positive macrophages in the tissue microenvironment." (PMID 38572322, 2024).
state anxiety (1 paper, 2020). "Thus the involvement of enhanced hippocampal CD68 expression, and thereby microglial phagocytic activity (CD68+Iba1+), previously demonstrated in state anxiety is now also supported in trait anxiety model." (PMID 32732969, 2020).
status epilepticus (1 paper, 2024). Status epilepticus is defined as a continuous seizure lasting more than 30 min, or two or more seizures without full recovery of consciousness between any of them. "Finally, CD68-positive activated microglia were much less prominent than shortly after status epilepticus and highly variable." (PMID 37874479, 2024).
Still disease (1 paper, 2021). "Recent studies have found that NETs can promote CD68 + macrophage activation in adult Still disease, while microglia are macrophages in the central nervous system." (PMID 33994918, 2021).
stomach diseases (1 paper, 2022). "Furthermore, GPR35 in CTSB+ and CD68 + macrophage for EGC had a notable high expression level when compared to those of other stomach diseases." (PMID 36333291, 2022).
T cell deficiency (1 paper, 2022). "In contrast to T cell deficiency, the recurrent tumors were significantly enriched for markers of tumor-associated neutrophils (TANs; eg., CD177, ELANE), tumor-associated macrophages (TAMs; eg., MRC1, CD68), and immune suppressive myeloid cells (MDSCs; eg., ARG1, CXCR4)." (PMID 35919862, 2022).
T-cell lymphomas (1 paper, 2015). "Since MS may express T-cell markers (such as CD43, CD45, CD4, and CD7), immunohistochemical expressions of MPO, lysozyme, and CD68 should be analyzed for their distinction from T-cell lymphomas." (PMID 25805673, 2015).
TB meningitis (1 paper, 2022). "Similar findings were noted in a patient with TB meningitis who underwent brain biopsy for clinical reasons, demonstrating parenchymal lesions with multinucleated giant cells and CD68+ cells (a marker of microglia/macrophages)." (PMID 35085105, 2022).
Tinnitus (1 paper, 2023). Tinnitus is an auditory perception that can be described as the experience of sound, in the ear or in the head, in the absence of external acoustic stimulation. "For example, there was a trend toward greater staining for KCNQ3, NLRP3, and CD68 and lower staining for PREX2 and APLN in the VS samples associated with tinnitus compared to those without tinnitus." (PMID 37048724, 2023).
tuberculous peritonitis (1 paper, 2016). A form of peritonitis seen in patients with tuberculosis, characterized by lesion either as a miliary form or as a pelvic mass on the peritoneal surfaces. "The histological morphology of localised tuberculous peritonitis may show the presence of Langerhans cells, and the immunohistochemical stains usually show the cells to be CD68 positive." (PMID 27069474, 2016).
undifferentiated nasopharyngeal carcinoma (1 paper, 2024). "The positive CD1a and CD68 antigen-presenting cells were observed in most cases of undifferentiated nasopharyngeal carcinoma (88%), being between 5 and 15% of the peri- and intratumor inflammatory infiltrate, with an intratumor predominance." (PMID 38611634, 2024).
uremia (1 paper, 2016). A clinical syndrome associated with the retention of renal waste products or uremic toxins in the blood. "In the remnant kidneys from NX mice, flow cytometry revealed an increase in the number of monocyte-like cells (CD68+F4/80-), CD4+, and CD8+ T-cells, suggesting that moderate uremia induced kidney inflammation." (PMID 27992511, 2016).
uterine serous carcinomas (1 paper, 2023). "This trend was not as prominent for CD8+, FOXP3+, or CD68+ immune cells in this cohort of uterine serous carcinomas." (PMID 36672477, 2023).
visceral leishmaniasis (1 paper, 2024). A severe form of leishmaniasis characterized by irregular bouts of fever, substantial weight loss, swelling of the spleen and liver, and anemia (which may be serious). "Macrophages resident in the liver (Kupffer cells) are reservoirs of the intracellular amastigote form in visceral leishmaniasis, characterized by the expression of characteristic macrophage markers (F4/80, CD14, CD68, CD11b)." (PMID 38966642, 2024).
Whipple disease (1 paper, 2026). A systemic infection caused by the Gram-positive bacterium Tropheryma whipplei. "Histology identified periodic acid-Schiff and CD68-positive foamy macrophages with negative Ziehl-Neelsen staining, confirming Whipple's disease." (PMID 41647925, 2026).
tumor (2,398 papers, 2002 to 2026). "Tumor-associated macrophages (TAMs) in ccRCC are abundant and phenotypically diverse, with CD68 marking general macrophage presence and CD163 indicating alternatively activated, immunosuppressive (M2-like) subsets." (PMID 41846920, 2026). "The immunohistochemistry for detecting components of the tumor microenvironment reveled the infiltration of tumor-associated macrophages (CD68, CD163) and tumor-associated fibroblasts (vimentin, SMA) in the tumor sample." (PMID 40433378, 2025). "Using CD68 as a macrophage marker in the panel and cytokeratin for tumour cells, the PD-L1 expression associated with non-tumour cells was highlighted." (PMID 41315839, 2025). "CD68, a glycoprotein predominantly expressed in macrophages, has been implicated in various cancers due to its role in modulating immune responses and tumor-associated inflammation." (PMID 40918116, 2025). "CD68, a macrophage marker, is present in the margin and core, indicating tumor-associated macrophage (TAM) infiltration throughout the tumor." (PMID 40431665, 2025). "We selected two biomarkers grounded in clinical research: PD-L1 expression and CD68 tumor-associated macrophages (TAMs)." (PMID 40558790, 2025). "The density and spatial distribution (i.e., distance) between CD8+ T cells, which are pivotal for tumor cell cytotoxicity, and CD68+ macrophages, particularly tumor-associated macrophages that play a critical role in the TME, were analyzed." (PMID 40422184, 2025). "This study proposes a Green Learning (GL) framework for approximating tissue-based biomarkers from CT scans, focusing on the PD-L1 expression and CD68 tumor-associated macrophages (TAMs) in ccRCC." (PMID 40558790, 2025). "Increased CD163+ and CD68+ cell count (representing M2 type macrophages and all tumour associated macrophages respectively) and increased MCSF and CCL2 expression, in both LARC biopsy and resection specimens, were associated with inferior overall survival." (PMID 41487587, 2025). "Further analysis revealed that high ALG3 expression was associated with reduced infiltration of CD8+ T cells and CD68+ macrophages in both tumor and stromal areas, while positively correlating with increased infiltration of FOXP3+ regulatory T cells (Tregs)." (PMID 40475760, 2025). "IHC analysis was performed on the tissue sections for identification of T-helper (CD4) and cytotoxic T lymphocytes (CD8), and of tumor-associated (CD68; resident macrophage) and M1-polarized macrophages (L1/MAC387)." (PMID 40146757, 2025). "To explore this, we analyzed the association between CMTM4 expression and CD45+ tumor‐infiltrating leukocytes (including CD68+ macrophages, CD19+ B cells, CD8+ T cells, and FOXP3+ regulatory T cells [Tregs]) in the TCGA‐OC cohort." (PMID 40433989, 2025). "Spatial transcriptomic and immunofluorescence analyses confirmed the co-localization of ALDOA with CD68 + tumor-associated macrophages (TAMs)." (PMID 41239433, 2025). "A lower number of tumor infiltrating CD68+ macrophages was associated with resistance to post‐surgery treatment with SRLs (48/HPFs, IQR: 22.9) than in patients responsive to post‐surgical SRL treatment (80/HPFs, IQR: 51, p = .005)." (PMID 40789673, 2025). "The study also indicated the presence of tumor macrophages (CD68+CD163+CSF1R+SIGLEC5+) associated with immunotherapy resistance." (PMID 40404633, 2025). "It primarily accumulates on CD68+ tumor‐associated macrophages within the TIME, leading to a dysregulated immune balance and impaired activation of CD8+ T cells." (PMID 41223031, 2025). "An association between CD68+ TAMs and the relative risk of tumor recurrence was also observed, while the odds of cancer-related death were almost doubled in CD68+/iNOS- patients." (PMID 40508145, 2025). "As expected, CD3+ TILs and CD68+ tumor-associated macrophages (TAMs) were predominantly located in the CK– stromal tissue areas and showed variable marker profiles." (PMID 40459946, 2025).
tumor (continued). "Given LGALS9 upregulation in immune-hot tumors, we assessed tumor-associated macrophages via CD68 (pan-macrophage marker) and CD163 (M2 macrophage marker) IHC to evaluate their contribution to an immunosuppressive microenvironment." (PMID 41332664, 2025). "We found that TMEM115 protein levels in tumor tissues were positively associated with CD68+ (R = 0.283, P < 0.001) and CD68+CD163+ (R = 0.145, P = 0.046) macrophages." (PMID 40552281, 2025). "CD68 is a macrophage marker, particularly M2-polarized tumor-associated macrophages (TAMs), which are associated with immunosuppression, extracellular matrix remodeling, and poor prognosis in OSCC." (PMID 41259576, 2025). "Tumor-associated macrophages (TAMs), particularly the M1 (CD68+) and M2 (CD163+) subtypes, play critical roles in inflammation, fibrosis, and immune modulation." (PMID 41239536, 2025). "For instance, CD68+ TAMs have been associated with therapy resistance and promote immunosuppressive environments that favor tumor growth." (PMID 40599139, 2025). "Spatial transcriptomics and immunofluorescence staining further confirm the co-localization of ALDOA with CD68+ tumor-associated macrophages, suggesting a direct role in macrophage-mediated immune modulation." (PMID 41239433, 2025). "Higher CD68+ staining in tumor cell nests was associated with both locoregional and distant recurrence." (PMID 39825956, 2025). "CDA expression corresponded with either the CD206+ immunosuppressive percentage or tumor border and center CD68+ tumor–associated macrophage infiltration in two homogeneous categories of PDAC patients." (PMID 40011298, 2025). "Increased expression of CD68 in tumor tissues has been associated with favorable survival outcomes in head and neck cancers." (PMID 39682556, 2024). "LC3B correlated only with CD8+ cytotoxic T lymphocytes whereas, HMGB1 correlated with both local and peritumoral infiltrates involving FOXP3+ regulatory T cells and CD68+ tumor-associated macrophages." (PMID 39830522, 2024). "In contrast, CD68 POS in the tumor was associated with an HR < 1 for comparison of categories 2 or 3 versus 0/1." (PMID 36811271, 2024). "In the myeloid compartment, stromal CD68+ tumour-associated macrophages (TAMs)were reduced in EC, whereas CD163+ M2 were increased." (PMID 39685707, 2024). "The scores of CD3, CD4, CD8, and CD68 was assessed to know the degree of tumor infiltration lymphocytes (TILs) or tumor-associated macrophages (TAMs) infiltration, which was graded 0-12." (PMID 38370388, 2024). "Our results suggested that a high CD68+ TAMs density in the tumor microenvironment was significantly associated with poor prognosis (OS and DFS) than a low CD68+ TAMs density." (PMID 38501293, 2024). "CD68 is a marker of macrophages and has been implicated with tumor-associated macrophages (TAMs) in AML." (PMID 38582086, 2024). "CD68 + tumor infiltrating immune cells were associated with a higher PLR and higher PLR values seemed to be linked with fewer residual viable tumor cells." (PMID 39138484, 2024). "On the other hand, the accumulation of therapeutic liposomal nanoparticles inside tumor microenvironment theoretically enhances the susceptibility to chemotherapy and/or radiotherapy of cancer cells, by hampering pro‐tumor activities of CD68‐positive TAMs." (PMID 39552192, 2024). "The number of nuclei exhibiting positive staining with DAPI (blue) was designated as total cells, and CD68 (Cy3 red fluorescence) + CD86/CD163 (FITC green fluorescence) double fluorescent staining was utilized to label tumor-associated macrophages." (PMID 39531417, 2024). "We assessed the prognostic role of all tumor-associated macrophages, which express CD68, and their pro-tumor M2 subset, expressing CD163 individually and in combination." (PMID 38287290, 2024). "CD68+ macrophages, often referred to as tumor-associated macrophages (TAMs), can influence the tumor microenvironment and impact cancer progression." (PMID 39330005, 2024).